NTRK3 (neurotrophic receptor tyrosine kinase 3)
Diseases named in the same sentence as NTRK3 in open-access papers (continued):
Sharing a sentence is not in itself a finding about the gene and the disease.
ventricular septal defect (2 papers, 2021 to 2025). The presence of a defect (opening) in the septum that separates the two ventricles of the heart. "Study has suggested that NTRK3 played an important role in congenital heart defects, and mutations in NTRK3 may increase the risk of ventricular septal defect." (PMID 41234403, 2025).
angiosarcoma (1 paper, 2023). A malignant tumor arising from the endothelial cells of the blood vessels. "Here, we describe the first case of paediatric angiosarcoma harbouring a targetable NTRK3 fusion in the literature and demonstrate the first example of targeting this alteration in paediatric angiosarcoma." (PMID 36910630, 2023). "Our patient represents the first paediatric angiosarcoma harbouring a targetable NTRK3 fusion in the literature and demonstrates the first example of targeting this alteration in angiosarcoma using larotrectinib, an NTRK inhibitor." (PMID 36910630, 2023).
colorectal adenoma (1 paper, 2013). An adenoma that arises from the colon or rectum. "Since NTRK3 is frequently methylated in colorectal adenomas, we carried out a series of studies to determine if loss of NTRK3 could induce transformed behavior in normal colon epithelial cells." (PMID 23874207, 2013). "NTRK3's preferred ligand, NT-3, was found to be substantially suppressed in both colorectal adenomas and adenocarcinomas, presumably secondary to hypermethylation of the NT3 promoter region." (PMID 23874207, 2013). "We now demonstrate that NTRK3 is frequently methylated in colorectal adenomas and cancers." (PMID 23874207, 2013).
diabetic cardiomyopathy (1 paper, 2016). Diabetic cardiomyopathy is a disorder of the heart muscle in people with diabetes. "Moreover, down-regulation of Ntrk2 and Ntrk3 genes might also play a role in the development of diabetic cardiomyopathy." (PMID 27496100, 2016).
esthesioneuroblastoma (1 paper, 2022). "Patient 27 (esthesioneuroblastoma with NTRK3 amplification) who was treated with the TKI crizotinib developed an altered taste, weight loss, nausea, color perception disturbances, swelling of the right lower leg of unclear etiology, liver enzyme elevations and neutropenia (CTCAE grade 2–3)." (PMID 35864412, 2022).
glioneuronal tumor (1 paper, 2023). "More recently, a novel MC of glioneuronal tumor (called the “glioneuronal tumor, not otherwise specified, subtype A") harboring RTK (ALK, NTRK1, NTRK2, NTRK3, and MET) fusions and MAPK (RAF1) fusions have been isolated by DNA‐methylation profiling." (PMID 37349135, 2023).
gliosarcoma (1 paper, 2020). A rare histological variant of glioblastoma (WHO grade IV) characterized by a biphasic tissue pattern with alternating areas displaying glial and mesenchymal differentiation (WHO). "In case 2, Oncomine Comprehensive v3 analysis of the local left frontal gliosarcoma recurrence detected an EML4:NTRK3 fusion, a CDKN2A/B loss and an MRE11A alteration of unknown significance." (PMID 33353026, 2020).
Infertility (1 paper, 2022). "For WL chickens, the copy number deletion of CSMD1 and NTRK3 may be involved in the outstanding reproduction traits, because NTRK3 and CSMD1 have been reported to play crucial roles in follicle development, ovarian quality, and infertility in human and chicken." (PMID 35391799, 2022).
invasive ductal carcinoma (1 paper, 2025). "Lower NTRK3 expression was associated with higher T stage (p = 0.002), Black and Asian racial groups (p = 0.011), invasive ductal carcinoma (p < 0.001), and luminal subtype (p < 0.001) significantly." (PMID 40142285, 2025).
liver fibrosis (1 paper, 2025). "Previous work has demonstrated that targeting the neurotrophin-3/NTRK3 axis can suppress liver fibrosis by disrupting autocrine/paracrine HSC signaling." (PMID 40678531, 2025).
metanephric adenoma (1 paper, 2023). A benign, well-circumscribed renal cortical neoplasm affecting females more often than males. "Moreover, KANK1 has been discovered to fuse with neurotrophic receptor tyrosine kinase 3 (NTRK3) gene in patient samples with pathologically confirmed metanephric adenoma leading to a subset of B-Raf proto-oncogene, serine/threonine kinase (BRAF) mutations." (PMID 37731134, 2023).
metastasis (1 paper, 2026). The spread or migration of cancer cells from one part of the body (where they first appeared) to another. "Genomic analysis revealed site-specific correlations: MYC mutations with pleural metastasis, NTRK3 with brain metastasis, ALK with adrenal metastasis, and NTRK1 with intrapulmonary metastasis." (PMID 42187573, 2026).
metastatic cancer (1 paper, 2023). A carcinoma which has spread from the original site of growth to another anatomic site. "The ALKA-372-001, STARTRK-1, and STARTRK-2 studies evaluated both the safety and efficacy of orally administering entrectinib to adult patients with locally advanced metastatic cancer with NTRK1, NTRK2, NTRK3, ROS1, or ALK rearrangements." (PMID 37111737, 2023). "The studies evaluated both the safety and efficacy of orally administering entrectinib to adults with locally advanced metastatic cancer with NTRK1, NTRK2, NTRK3, ROS1, or ALK rearrangements." (PMID 37111737, 2023).
neuroendocrine carcinoma (1 paper, 2026). A malignant neuroendocrine neoplasm composed of cells containing secretory granules that stain positive for NSE and chromogranin.
neuroendocrine tumors (1 paper, 2023). "And in the existed literatures, the prevalence of NTRK3 was only 0.1% in neuroendocrine tumors." (PMID 36703785, 2023).
oral cancer (1 paper, 2020). "Of these, NTRK3 and SLC7A5 were earlier identified to be associated with oral cancer." (PMID 33317464, 2020).
Pan (1 paper, 2023). "The relative proportion of NTRK1, NTRK2 and NTRK3 fusions varied across Pan Cancer cohorts but NTRK3 fusions were generally the most frequent." (PMID 36914665, 2023).
pancreatic ductal adenocarcinoma (1 paper, 2021). An infiltrating adenocarcinoma that arises from the epithelial cells of the pancreas. "In this case, we first reported targeted comutation of somatic novel KANK1-ALK, UPP2 intergenic NTRK3 fusion, and pathogenetic germline BRCA1 mutation in a pancreatic ductal adenocarcinoma patient." (PMID 34671564, 2021).
small cell carcinoma of the ovary (1 paper, 2023). "Moreover, paraneoplastic hypercalcemia, while being specifically associated with the ETV6::NTRK3 fusions, is also significantly associated with SMARCA4 inactivation in the majority of small cell carcinoma of the ovary, hypercalcemic type." (PMID 36690805, 2023).
triple-negative breast carcinoma (1 paper, 2025). An invasive breast carcinoma which is negative for expression of estrogen receptor (ER), progesterone receptor (PR), and human epidermal growth factor receptor 2 (HER2). "Additionally, NTRK3 was upregulated significantly in triple-negative breast cancer (TNBC) patients (P-value: .0279)." (PMID 40061872, 2025).
upper tract urothelial carcinomas (1 paper, 2024). "Correlation of NTRK3 expression with clinicopathological characteristics in patients of upper tract urothelial carcinoma." (PMID 38593276, 2024).
uveal melanoma (1 paper, 2024). A melanoma derived from melanocytes of the uveal tract. "Increased NTRK1 expression was a risk factor for uveal melanoma (UVM), and high NTRK2 and NTRK3 expression was associated deceased OS, DSS, and PFI in bladder urothelial carcinoma (BLCA)." (PMID 38357305, 2024).
tumor (215 papers, 1996 to 2026). "This includes low prevalence biomarkers such as NTRK1, NTRK2, and NTRK3 (NTRK1/2/3) fusions as well as higher prevalence complex biomarkers such as tumor mutational burden-High (TMB-H)." (PMID 40748987, 2025). "In this article, we evaluated the prognostic value of NTRK3 by analyzing its association with clinicopathological features and tumor-infiltrating immune cells (TIICs) in BC." (PMID 40142285, 2025). "In 2024, disease progression was observed with residual KIT mutation (VAF 1.10%) and new-onset ETV6:NTRK3 fusion (VAF 35.29%) detected by circulating tumor DNA (ctDNA) analysis." (PMID 40900786, 2025). "We utilized an RNA hybrid capture-based NGS approach designed to detect fusions and splice variants in 55 genes including NTRK1, NTRK2, and NTRK3 fusions, resulting in a detection rate of 0.35% across a real-world, pan-tumor cohort." (PMID 40385986, 2025). "Lower NTRK3 expression was associated with a higher T stage, indicating larger tumor size and greater metastatic potential." (PMID 40142285, 2025). "Activation of the NTRK2 and NTRK3 signalling pathways has been associated with tumour invasion, resistance to therapy, and the progression of numerous malignancies, including BC." (PMID 40061872, 2025). "Combination of selpercatinib with the dual NTRK/ALK inhibitor entrectinib reduced the tumor burden, which was followed by appearance of NTRK3 solvent-front G623R mutation." (PMID 38438731, 2024). "Further molecular analysis with the Oncomine Comprehensive Assay v3 (OCAv3) and ThyroSPEC revealed an ETV6::NTRK3 fusion-positive tumor harboring an additional TERT promoter mutation c.-124C>T, with no other genetic alterations." (PMID 38642578, 2024). "NTRK3, located on chromosome 15q25, has been wildly reported as a tumor suppressor implicated in the modulation of cell growth, invasion, and migration in a diverse array of tumors, including HCC." (PMID 36959801, 2023). "Molecular profiling of the tumor identified a novel R-Spondin2 RNA fusion and NTRK3 mutation that can be potentially targeted for treatment." (PMID 37626821, 2023). "Exploring gene mutations related to better OS, NTRK3 protein expression was previously positively associated with higher tumor immune and stromal scores, a great variety of immune lymphocytes, improved immune response, and, ultimately, with better survival." (PMID 36358851, 2022). "ETV6/NTRK3 was associated with follicular tumor architecture only (OR = 10.15 (1.26–81.81), p = 0.011)." (PMID 34282777, 2021). "We then analyzed the association of NTRK3-MT with clinical characteristics and found the tumor mutation burden (TMB) to be significantly higher in both NTRK3-MT cohorts." (PMID 32903385, 2020). "Then, the TMB was evaluated in the ICI-treated LUAD and TCGA-LUAD cohorts, and as expected, it was significantly higher in the NTRK3-MT groups, consistent with previous studies showing that tumor immunity is positively associated with the TMB." (PMID 32903385, 2020). "Perhaps most importantly, NTRK3 inhibited colony formation in soft agar colony formation assays and suppressed the growth of tumor xenografts, which are hallmark in vitro effects of tumor suppressor genes." (PMID 23874207, 2013).
tumor (continued). "The neurotrophin receptor encoded by NTRK3 participates not only in neuronal development but also critically regulates osteogenic differentiation of MSCs, indicating its potential role in tumor matrix remodeling through modulation of MSC differentiation fates." (PMID 40598621, 2025). "We also explored the association between NTRK3 expression and tumor-infiltrating immune cells." (PMID 40142285, 2025). "In addition, one tumor each had a NTRK3 fusion (ETV6-NTRK3), a PTEN deletion, an FGFR1 GOF mutation (K654E), a CHEK2 LOF mutation (T367fs*), and an Aurora kinase A fusion (AURKA-CSTF1)." (PMID 38730662, 2024). "Mutations in NTRK3 promote tumor formation and progression in colorectal cancer." (PMID 38593276, 2024). "Furthermore, based on our data, NTRK1 fusion-positive carcinomas were significantly associated with a higher frequency of tumor multifocality and distant metastases, and were more invasive than the carcinomas harboring a NTRK3 fusion." (PMID 33923728, 2021). "NTRK gene fusions involving NTRK1, NTRK2 and NTRK3 (encoding receptor proteins TRKA, TRKB and TRKC, respectively) are responsible for many neoplasms in both adults and children, including rare cancers such as secretory breast carcinoma and infantile fibrosarcoma." (PMID 33921237, 2021). "Interestingly, the methylation of this specific region was shown to be associated with the loss of NT3-dependent tumor suppressor gene function of NTRK3 in our previous in vitro and in vivo study." (PMID 33593392, 2021). "In addition, mutations in CDKN1B and NTRK3 genes have been recently found associated with this tumor." (PMID 34804623, 2021). "To further explore whether NTRK3 mutations are involved in important tumor-related biological pathways and processes, we compared levels of signaling pathway enrichment between the NTRK3-MT and NTRK3-WT groups." (PMID 32903385, 2020). "Consistent with this hypothesis, our data in the present study has demonstrated that tumours with the BRAFV600E mutation were significantly smaller than BRAFV600E-negative cases including RET/PTC or ETV6/NTRK3." (PMID 26584635, 2015). "This means that NTRK3 and ETV6 fusions might be causally related to the extent of the tumor mass, and a primary total thyroidectomy might be more beneficial over a subtotal one for those patients having either NTRK3 or ETV6 fusion mutation within the PTC tissue." (PMID 39409115, 2024). "Its aberrant activation and presence in NTRK3 fusion proteins induces the epithelial to mesenchymal transition program, increases the cancer cell growth rate and oncogenic capacity activating different pathways associated with tumor development and progression." (PMID 36289793, 2022). "Additionally, we reported that the size of the tumor, positivity for NTRK3 or NTRK1 fusion, the presence of metastases and late mutation events may provide prognostic information for patient outcomes." (PMID 33923728, 2021). "Materials and Methods: We conducted a comprehensive analysis of NTRK3 expression in BC using the Tumor Immune Estimation Resource, Gene Expression Profiling Interactive Analysis 2, and Kaplan–Meier Plotter databases." (PMID 40142285, 2025). "Second, although we observed a correlation between NTRK3 expression and tumor progression, we lack detailed mechanistic insights into how NTRK3 influences BC." (PMID 40142285, 2025). "In ALK-negative tumours, alternative drivers have been identified, including ROS1, RET, NTRK3 and PDGFRB rearrangements or mutations." (PMID 40980125, 2025). "NTRK3 showed a significant positive correlation with M1 macrophages, which are generally considered to have anti‐tumor properties." (PMID 40600620, 2025). "The NTRK2 gene was not examined by FISH, but NTRK2 gene fusions are reported to be even much rarer than NTRK1 and NTRK3 gene rearrangements in other neoplastic diseases." (PMID 40235191, 2025).
tumor (continued). "NTRK1, NTRK2, and NTRK3 gene fusions are rare oncogenic driver alterations found in diverse tumor types of adults and children." (PMID 40385986, 2025). "Interestingly, the heterogeneous staining pattern in ETV6::NTRK3 fusion-associated PTCs tends to be stronger in the tumor periphery and becomes weaker to subdiagnostic towards the center, a phenomenon that might be dismissed as artifactual in nature and considered to be non-diagnostic." (PMID 40111709, 2025). "On the other hand, NTRK3 expression displayed higher expression in left-sided tumours, higher nodal stage (≥N1), late overall (TNM) disease stage, MSS state and low TMB cases." (PMID 41155675, 2025). "Tumor stage, lymphovascular invasion, and NTRK3 expression were significant factors in the univariate analysis of all outcomes." (PMID 38593276, 2024). "The mRNA expression of SPIB, PLK1, and CD24 is upregulated in clinical tumor tissues, whereas NTRK3 and EDA2R mRNA expression is downregulated." (PMID 39596658, 2024). "In this study, two NTRK3-null DSRCT cell lines showed reduced tumor viability, supporting inhibition of NTRK3 by entrectinib and reprotrectinib." (PMID 38200576, 2024). "NTRK3 is crucial to the development of the nervous systems, cancer and tumor formation and advancement stimulated by the modifications of NTRK3." (PMID 38739758, 2024). "Instead, further molecular genetic testing showed that the tumor harbored a rare EWSR1::CREM fusion combined with a previously unreported IRF2::NTRK3 fusion." (PMID 37274229, 2023). "Nine tumors harbored an NTRK1 fusion with different fusion partners (4 × TPM3, 4 × LMNA, 1 × SFPQ), one tumor harbored an ETV6::NTRK3 fusion." (PMID 37067589, 2023). "Molecular profiling of the tumor and ctDNA revealed a novel MATN2-RSPO RNA fusion and a novel NTRK3 mutation, respectively." (PMID 37626821, 2023). "Based on our experience within this screening project and with other tumor tissues and previous reports, nuclear Trk staining is probably specific to NTRK3-fused cancers." (PMID 37296928, 2023). "Similar to other tumor types, TPM3::NTRK1, EML4::NTRK3 and ETV6::NTRK3 fusion variants represented the majority of NTRK1–3 translocations identified in this study." (PMID 37686416, 2023). "Neurotrophic tyrosine receptor kinase (NTRK) fusions are validated oncogenic drivers of various adult and pediatric tumor types, including NTRK1, NTRK2, and NTRK3, which encode the TRK proteins TRKA, TRKB, and TRKC, respectively." (PMID 37188179, 2023). "One case showed a green 5′ and red 3′ NTRK3 split signal in ≥50% of the tumor cells; therefore, it was defined as NTRK-positive, and it has been reported elsewhere." (PMID 37190044, 2023). "The results revealed that mutations in GNAQ, SEPTIN 6, NTRK3, and IKZF1 occur only in tumor samples." (PMID 35864526, 2022). "NTRK1, NTRK2 or NTRK3 can be found as oncogenic drivers in a wide range of paediatric and adult tumours." (PMID 33620682, 2021). "NTRK fusions: NTRK1, NTRK2, and NTRK3 are actionable drivers of tumor growth, and these genes encode the tropomyosin receptor kinase (TRK) family of receptor tyrosine kinases, proteins TRKA, TRKB, and TRKC, respectively." (PMID 33673070, 2021). "One of the FISH-positive cases had a separate NTRK3 FISH signal in 88% of the tumor cells, and its IHC result was strong nuclear staining in all the tumor cells." (PMID 34490345, 2021). "We plan to extend these findings in future work using LUSC patient tumor samples to examine if NTRK3 detection correlates with SLITRK3 amplification and high levels of lung CSC markers, such as CD133 or ALDH1." (PMID 35006496, 2021). "The other FISH positive case identified an NTRK3 separation signal in 88% of the tumor cells, and IHC results indicated a strong and diffuse nuclear stain in almost all tumor cells." (PMID 34490345, 2021).